IL9 (interleukin 9)
Diseases named in the same sentence as IL9 in open-access papers (continued):
Sharing a sentence is not in itself a finding about the gene and the disease.
Allergy (continued). "Multiple reports suggested a role of IL9 in lung inflammation and allergy." (PMID 33801620, 2021). "After activation by basophils, ILC2s not only clearly accumulate but also enhance the expression of CCL11, IL-5, IL-9 and IL-13, which further leads to the accumulation of eosinophils and promotes other inflammatory responses in subjects with allergic diseases." (PMID 34177881, 2021). "It is suggested that IL-9 mediates the mast-cell component of the allergic reaction." (PMID 31395084, 2019). "These effector-TH2 cells express higher level of IL4, IL5, and IL-9 compared with “classical” TH2 cells and thus could represent pathogenic cells mediating allergy through the IL-33–ST2 signaling pathway." (PMID 29988522, 2018). "The cis-regulatory elements of the gene encoding IL-9, a cytokine that promotes allergy, autoimmune inflammation and tumor immunity, have not been defined." (PMID 30442929, 2018). "Thus, the Il9ΔCNS-25 mice present a useful model to further explore IL-9-specific responses in allergic disease." (PMID 30442929, 2018). "IL-9 has been implicated in a number of immune or inflammatory diseases such as parasitic infection, allergy, and asthma disease; however, the function of IL-9 in tumor immunity remains unclear and controversial." (PMID 28349057, 2017). "Although IL-9 is involved in inflammatory responses due to allergy or classical Th2 responses, its role in bacterial infections remains unclear." (PMID 27479584, 2016). "Furthermore, the influence of MSCs on IL-9 expression can open new possibilities for MSC-based therapy in allergic diseases." (PMID 25559824, 2015). "The important role of IL-9 in autoimmunity and allergy may provide important clues, especially in the light of recent hypotheses that connect prostate inflammation with cancer." (PMID 23991210, 2013). "Despite increasing evidence, that IL-9 may be involved in allergy, only few studies have been performed using an IL-9 antagonist to test its possible therapeutic efficacy in the treatment of allergic inflammation." (PMID 15823208, 2005). "Treatment with a monoclonal anti-IL-9-antibody during the sensitization process attenuates the development of airway allergic inflammation and airway hyperresponsiveness in mice exposed to allergen at a later time, implying a role of IL-9 in the development of allergy." (PMID 15823208, 2005). "Given the extensive evidence indicating IL-9 may be a candidate cytokine in the pathogenesis of allergic diseases, further research into the regulation of IL-9 production is warranted." (PMID 15840176, 2005). "The findings suggest that the beneficial effects of glucocorticoids in the treatment of allergic diseases may, in part, be mediated by inhibition of IL-9 production." (PMID 15840176, 2005). "In addition to allergic disease, increased IL-9 expression, Th9 cell expansion, and IL-9+ ILC2 expansion have also been reported in autoimmune diseases like inflammatory bowel disease (IBD), systemic sclerosis, rheumatoid arthritis (RA), psoriatic disease, and vasculitis." (PMID 38825637, 2024). "We found that IL-9 secretion dropped after LPS stimulation in CBMCs from neonates in the farming group, which might be associated with their non-susceptibility to allergic diseases." (PMID 30140427, 2018). "Recently, it has been suggested that IL-9 might play a role in allergy." (PMID 15823208, 2005). "But additional discrete T helper cell subsets are involved in human allergy; Th9 cells, induced by TGF‐β and IL‐4, secrete IL‐9 which enhances the growth of mast cells, and can lead to inflammation in the lung and intestines, including intestinal anaphylaxis." (PMID 29164823, 2018). "Th9 cells, a new member of CD4+ T cell family which is characterized by its specific cytokine IL-9 and transcription factors PU.1 and IRF-4, have been known recently to have a critical role in allergic diseases, and cancers as well as the parasitic infection." (PMID 26509179, 2015).
Allergy (continued). "Recent work shows the presence of a local allergy reaction in acute phlegmonous appendicitis (APA), with an elevation of Th2 cytokines IL-4, IL-5, and IL-9 in appendicular lavage fluid (ALF), a new concept for evaluating the local immune response in AA developed by our group." (PMID 41596388, 2026). "Finally, IL-9-producing mucosal mast cells (MMC9), distributed around the microvasculature of the intestinal mucosa, participate in allergic diseases and promote food allergy mediated by IgE, mainly by secreting a variety of cytokines, including IL-9." (PMID 34944921, 2021). "IL-9 is a mostly T-cell produced cytokine that has a functional role in allergic disease and resistance to intestinal nematodes, but no data is yet available on its role in heart disease." (PMID 21418620, 2011). "It is interesting that in preseasonal ASIT regimen, IL-9 production has a negative correlation with the manifestation of allergic reactions, which may be related to the induction of Th17 cells and in resolution of inflammation via Tregs." (PMID 36439113, 2022). "Pleiotropic IL-9 can regulate the function of T cells, B cells, mast cells and airway epithelium cells by activating the STAT1, STAT3 and STAT5 signaling pathways, which are involved in the progression of tumor diseases, allergic diseases, inflammatory, and autoimmune diseases." (PMID 32228589, 2020). "Because ongoing studies are still defining the role of IL-9 in autoimmune diseases, the role of IL9 epigenetics in autoimmunity is not as well investigated as it is in allergy." (PMID 38825637, 2024). "At variance with IL-2, IL-33 did not stimulate MC for IL-9/TGF-β production, a finding indicating a minor contribution of the IL-33/MC axis in promoting inflammatory allergy and pathology in response to the fungus." (PMID 28090087, 2017).
COVID-19 (71 papers, 2020 to 2026). A disease caused by infection with severe acute respiratory syndrome coronavirus 2. "Here authors show in a mouse model of SARS-CoV-2 infection that IL-9, predominantly produced by helper T cells, plays a critical pathogenic role in COVID-19 via an inflammatory pathway involving the transcription factor Foxo1." (PMID 37429848, 2023). "Symptoms of severe COVID-19 have been associated with a cytokine storm with high levels of IL-17, IL-10, IL-1β, IL-2, IL-7, IL-8, IL-9, among many other pro-inflammatory cytokines." (PMID 33071815, 2020). "We hereby displayed that PLWH with acute COVID-19 feature a distinct plasma cytokine profile (with higher Th1/Th2/Th17-like cytokines, yet lower IL-2 and IL-9), which, in turn, is associated with poorer control of SARS-CoV-2 replication/dissemination and worse respiratory insufficiency." (PMID 38188525, 2024). "In detail, systematic reviews and meta-analyses associated the excessive and uncontrolled release of IL-4, IL-8, IL-9, and Eotaxin with more severe COVID-19." (PMID 39125829, 2024). "A clinical study characterizing plasma immune profiles of individuals with TB and COVID-19 versus singular TB or COVID-19 discovered an immune signature composed of TNF-α, MIP-1β, and IL-9 that discriminated co-infection from COVID-19 alone." (PMID 38966641, 2024). "We found that the NfL levels are significantly predicted by a panel of circulating cytokines/chemokines, including CRP, IL-4, IL-8, IL-9, Eotaxin, and MIP-1ß, which are highly up-regulated during COVID-19 and are associated with clinical outcomes." (PMID 39125829, 2024). "This is in line with the role of functional Tregs in reducing COVID-19 severity and the observed increase in IL-9 among patients who recovered from severe disease in our cohort." (PMID 37569646, 2023). "We show that IL-9 levels were elevated in active COVID-19 patients infected with ancestral strain during the first wave of pandemic in mid-2020." (PMID 37429848, 2023). "Similar to active COVID-19 patients, IL-9 was found to be upregulated in the lungs of SARS-CoV-2-infected hamster and ACE2.Tg mice." (PMID 37429848, 2023). "In co-infected patients:↑ TNF-α, MIP-1β, and IL-9 compared with COVID-19-only.↑ TNF-α, IL-1β, IL-17A, IL-5, FGF-basic, and GM-CSFcompared with TB-only.↓ specific response to SARS-CoV-2 and Mtb." (PMID 37662901, 2023). "In other investigations, cytokine IL-9 levels were shown to be higher in COVID-19 patient groups compared to healthy controls, contradicting our findings." (PMID 37015978, 2023). "Apart from the predictive power of the IFNγ/IL-9 ratio, this study’s findings indicate that severe patients with COVID-19 expressed high levels of all tested cytokines." (PMID 37569646, 2023). "In line with this, we found that the expression of IL-9 was found to be increased in the PBMCs of active COVID-19 patients." (PMID 37429848, 2023). "In particular, in TB-COVID-19 co-infected patients TNF-α, MIP-1β, and IL-9 showed significant elevated levels compared to COVID-19 only, and TNF-α had the highest discriminant power." (PMID 37662901, 2023). "On the other hand, urinary levels of IL-9, which can inhibit cytokine production during Th1 response and enhance T cell survival, were reduced in COVID-19 patients." (PMID 36359444, 2022). "The ratios of IFN-γ/IL-4, IL-12/IL-4, IFN- γ/IL-9, TNF-α/IL-4, IFN- γ/IL-5 and IL-12/IL-9 were lower ((≈30-, 11-, 8, 4-, 4-, and 3- fold differences respectively) in COVID-19 ICU patients as compared to HC subjects." (PMID 36363785, 2022). "An increase in serum levels of the Th2 cytokines IL-5 and IL-9 has been reported in COVID-19 ICU patients compared to HC." (PMID 36363785, 2022). "For instance, the ratios of IL-2/IL-5, IL-2/IL-10, IL-2/IL-9, IL-6/IL-5, IL-6/IL-10 and IL-6/IL-9 were considerably higher in COVID-19 ICU patients as compared to HC subjects (≈8571-, 4800-, 4444-, 378-, 521-, and 172-fold differences respectively)." (PMID 36363785, 2022).
COVID-19 (continued). "The ratios of IL-12/IL-4, IL-12/IL-10, IL-12/IL-5, IL-12/IL-9, IL-2/IL-10, and IL-2/IL-9 were substantially higher in COVID-19 ICU patients compared with HC subjects (≈5660-, 5333-, 2100-, 600-, 69-, and 24-fold differences, respectively)." (PMID 36363785, 2022). "The chest CT image of COVID-19 patients showed ground-glass opacity, and compared with healthy adults, the plasma concentrations of IL-1β, IL-7, IL-8, IL-9, IL-10, IFN-γ, TNF-α, and VEGF of COVID-19 patients were all upregulated." (PMID 35874688, 2022). "Our results showed that critically ill COVID-19 patients had increased serum levels of IL-1β, IL-1RA, IL-6, IL-9, and CXCL10, and lower levels of IL-2 and IL17A as compared to healthy volunteer donors." (PMID 33995342, 2021). "In fact, patients with COVID-19 display a pro-inflammatory (IL-1β, IL-6, IL-7, IL-8, IL-9, FGF, G-CSF, GM-CSF, IFN-ɣ, CXCL10, CCL2, CCL3, CCL4, PDGF, TNFα, and VEGF) and regulatory cytokine profile (IL-10 and TGFβ; cytokine storm)." (PMID 33995342, 2021). "Typically, the critical COVID-19 patients reported with higher plasma concentrations of IL-7, IL-8, IL-9, basic fibroblast growth factor, granulocyte colony-stimulating factor and granulocyte-macrophage colony-stimulating factor were in high fatality." (PMID 33604601, 2021). "The progress of COVID-19 from mild illness to severe form depends on the circulatory levels of inflammatory cytokines and chemokines such as IL-7, IL-8, IL-9, IL-10, GCSF, GMCSF, TNFα, and VEGFA." (PMID 34786427, 2021). "Whereas IL-9 participates in the resolution of inflammation through type 2 innate lymphoid cells, IL-12 was detected in asymptomatic or mild COVID-19 and is suggested to play a key role in protection from cytokine storm and severe disease." (PMID 34759825, 2021). "Also, in PLWH/COVID-19, serum levels of a different set of interleukins (IL-5, IL-6, IL-9, and IL-15) and chemokine CXCL10 were upregulated." (PMID 41516165, 2025). "In PLWH/COVID-19, elevated IL-6, IL-5, IL-9, and IL-15 interleukins compared to COVID-19-only could induce a strong immune response in these patients." (PMID 41516165, 2025). "However, there are limited data on the role of high IL-5 and IL-9 in PLWH/COVID-19 in COVID-19 outcome." (PMID 41516165, 2025). "A dysregulation in cytokine content has been linked to T cell exhaustion in patients who recovered from COVID-19 (n = 39), with higher levels of IL-1β, IL-1RA, IL-7, IL-8, IL-10, IFN-γ, and MIP-1α, and a decrease in IL-9, CCL11, MIP-1β, and RANTES, as compared with healthy controls (n = 43)." (PMID 38549752, 2024). "Our findings also indicated higher IL-9 levels in COVID-19 patients." (PMID 39061002, 2024). "When directly looking at the specific cytokines found to be able to predict the NfL levels (CRP, IL-4, IL-8, IL-9, Eotaxin, and MIP-1ß), the literature highlight that all the selected factors are highly up-regulated during COVID-19 and associated with clinical outcomes." (PMID 39125829, 2024). "Higher levels of TNF and IL-9 suggested co-infection and authors speculate it can help discriminate TB-COVID-19 from COVID-19 alone." (PMID 37841282, 2023). "Altogether, we identified one of the key mechanisms of T cell-mediated immunopathology in Covid19 by showing that Foxo1 and IL-9 controls two distinctive pathological features that critically contribute to the progression and severity of COVID-19—namely anti-viral pathway and airway inflammation." (PMID 37429848, 2023). "In line with this, we show that IL-9 was found to be increased in active COVID-19 patients." (PMID 37429848, 2023). "In particular, IFNγ and IFNγ/IL-9 ratios are powerful biomarkers of COVID-19 severity and may predict the potential for survival." (PMID 37569646, 2023). "This study aims to investigate the role of interleukin-9 (IL-9) in COVID-19 pathogenesis." (PMID 37429848, 2023). "Pneumonia is linked to blood levels of IL-1β, IL-7, IL-8, IL-9, and IL1-5 in COVID-19." (PMID 36111104, 2022).
COVID-19 (continued). "Exogenous IL-9 increases airway inflammation in Foxo1-deficient mice, while IL-9 blockade reduces and suppresses airway inflammation in SARS-CoV-2 infection, providing further evidence for a Foxo1-Il-9 mediated Th cell-specific pathway playing a role in COVID-19." (PMID 37429848, 2023). "We observed that Foxo1 and IL-9 expression is increased in active human Covid19 patients, and in the lungs of SARS-CoV-2-infected hamster and ACE2.Tg mice, suggesting that Foxo1-IL-9 axis might be critical for SARS-CoV-2 infection and lung inflammation." (PMID 37429848, 2023). "Meanwhile, the role of IL-9, the classical cytokine of Th9 cells, is unknown in COVID-19." (PMID 35674675, 2022). "The present data indicate that DPSC administration might be effective in patients with COVID-19-induced hyper-inflammation, due to the inhibition in the production of several cytokines by activated T lymphocytes, namely, IFNγ, TNFα, IL-2, IL-9, IL-10, IL-17A, IL-18, IL-21, and IL-27." (PMID 33634100, 2020). "Pro-inflammatory cytokines, such as IL-5, IL-6, IL-9, and IL-15, were elevated in PLWH/COVID-19 compered to COVID-19-only." (PMID 41516165, 2025). "Six chemokines (CXCL9, CXCL10, CCL4, CCL5, CCL27, and CXCL12) and eight interleukins (IL-1Ra, IL-2Ra, IL-3, IL-5, IL-9, IL-12p40, IL-15, and IL-16) were increased in both PLWH/COVID-19 and COVID-19-only." (PMID 41516165, 2025). "Similar overexpression of several cytokines (IL-1β, IL-7, IL-10, IL-17, IL-2, IL-9, IL-8, IL-9, IFN-γ, TGF-β, and some metalloproteinases) is seen in chronic periodontitis and COVID-19." (PMID 38251365, 2024). "Lastly, we identified altered production of BAL cytokines (IFN-γ, IL-9, and IL-1) that were also isolated in the BAL of patients with COVID-19-related acute respiratory distress syndrome." (PMID 38259435, 2023). "At baseline, for non-KTRs, differences in several cytokines and vascular mediators were observed when the COVID-19 patients were compared with the HCs, except for ADAMTS-13, myoglobin, IL-9, G-CSF, and TNF-α." (PMID 38005844, 2023). "Taken together, these findings reinforce the well-known pro-inflammatory storm observed in severe COVID-19 patients and further demonstrate unbalanced integrative networks with the simultaneous participation of IFN-γ, IL-1Ra and IL-9 on hospital admission." (PMID 36451835, 2022). "Cytokine profiles of PBMCs showed significantly lower levels of GM-CSF, IFN-γ, IL-6, IL-9, IL-10, IL-17A, and TNF-α (p < 0.0001) in COVID-19 ICU patients." (PMID 36363785, 2022). "At the time of admission, COVID-19 patients presented a complex and robust serum soluble mediator network, with a higher number of strong correlations involving IFN-γ, IL-1Ra and IL-9 observed in patients progressing to MV or death." (PMID 36451835, 2022). "Levels of pro-inflammatory (IFN-γ, IL-1β, IL-6, IL-9, IL-12p70, CCL11) and anti-inflammatory (IL-4, IL-5, IL-10, IL-13) cytokines, as well as VEGF, were higher in severely ill COVID-19 patients as compared to pandemic influenza A(H1N1) subjects." (PMID 33995342, 2021). "In addition, some authors hypothesize that cytokines and chemokines involved in T2 immune responses, like IL-13, IL-9 and Macrophage Inflammatory Protein-1 alpha and beta, might counteract the pool of proinflammatory cytokines involved in the pathogenesis of COVID-19." (PMID 33996694, 2021). "Among the statistically significant reduced cytokines exhibited by patients with COVID-19 compared to influenza patients were interferon-γ (IFN-γ), MIG, IL-1RA, IL-2R, G-CSF, IL-17a, IL-9, and MIP-1α." (PMID 33187979, 2020). "Significantly up-regulated levels of cytokines and chemokines including IL1-β, IL1RA, IL10, IL9, IL8, IL7, basic FGF2, GCSF, GMCSF, IFNγ, IP10, MCP1, MIP1α, MIP1β, PDGFB, TNFα, and VEGFA in blood, have been confirmed in COVID-19 patients." (PMID 33041797, 2020).